ATF6 (activating transcription factor 6)
Diseases named in the same sentence as ATF6 in open-access papers (continued):
Sharing a sentence is not in itself a finding about the gene and the disease.
cardiac hypertrophy (continued). "Importantly, Atf6b−/− gene-deleted mice appeared to show the same defects in cardiac hypertrophy, mobilization of ER protein chaperones, and ultimately underwent the same accelerated failure with pressure overload as their Atf6−/− counterparts." (PMID 30765833, 2019). "Therefore, QRICH1 may play a pivotal role in orchestrating protein synthesis and folding, as well as sustaining protein homeostasis, by modulating the transcription of ATF6 during cardiac hypertrophy." (PMID 40355839, 2025). "In considering other possible non-canonical roles for ATF6, a recent study set out to test whether the increase in protein synthesis and protein folding demand that occur during cardiac hypertrophy poses a challenge to the protein folding machinery, resulting in ATF6 activation." (PMID 32138230, 2020). "However, despite the evidence that Thbs4-mediated ATF6α activation is protective after acute injury, we did not observe that overexpression of Thbs4 mitigated phenotypic changes associated with cardiac hypertrophy." (PMID 30765833, 2019). "As described throughout this review, maintaining cardiac myocyte proteostasis is vital for cellular viability and function, and ATF6 has demonstrated efficacy as a therapeutic target for CVD and cardiac hypertrophy." (PMID 32138230, 2020). "Studies highlighting the protective roles of canonical gene targets of ATF6 have further fortified interest in pursuing ATF6-based therapeutics in clinically relevant disease models, namely AMI and pathological cardiac hypertrophy." (PMID 32138230, 2020). "In fact, physiological cardiac hypertrophy in mice subjected to free-wheel exercise was lower in the hearts of ATF6 cKO mice compared to control mice, supporting the hypothesis that growth stimuli activate ATF6-dependent genes that are required for cardiac myocyte growth." (PMID 32322217, 2020). "Previous studies have verified that ER stress is a pathological characteristic of cardiac hypertrophy, and the expression of related molecules such as GRP78, ATF6, CRT, and CHOP is increased significantly during cardiac hypertrophy." (PMID 27057269, 2016). "QRICH1 plays a pivotal role in cardiac hypertrophy by regulating ATF6, and QRICH1 may be a potential new therapeutic target for pathological cardiac hypertrophy." (PMID 40355839, 2025). "Recent unpublished work has found yet another non-canonical target of ATF6 in a model of volume overload-induced cardiac hypertrophy." (PMID 32138230, 2020). "Unexpectedly, we observed that eliminating the Atf6 or Atf6b genes resulted in a significant reduction in cardiac hypertrophy but function was not affected over this relatively short 2 week time period." (PMID 30765833, 2019). "However, activated ATF6 exhibits non-canonical roles in growth-driven during pressure overload-induced pathological cardiac hypertrophy through the ATF6-Rheb-mTORC1 axis." (PMID 40355839, 2025). "Thus, ATF6 plays a previously unappreciated role in cardiac hypertrophy via inducing the non-canonical target, Rheb (Steps 9 and 10)." (PMID 32138230, 2020). "This review focuses on the therapeutic potential of ATF6 in maintaining cardiac myocyte proteostasis by inducing canonical and non-canonical gene targets in CVD and, more specifically, cardiac hypertrophy." (PMID 32138230, 2020).
Cerebral ischemia (12 papers, 2015 to 2024). Restriction of arterial blood supply to the brain associated with insufficient oxygenation to support the metabolic requirements of the tissue. "Research has shown that ATF6α knockout mice exhibit more severe functional damage and a worse prognosis after myocardial ischemia or cerebral ischemia, indicating that ATF6 deficiency increases organ damage upon exposure to ischemia." (PMID 35602556, 2022). "This hypothesis is supported by studies in mouse models of cerebral ischemia, which reconfirm that ATF6 deficiency leads to more severe functional impairment and a worse prognosis, likely due to the inhibition of the protective effects of ATF6 against organ injury during ischemia." (PMID 37891634, 2023). "Previous research has demonstrated that ATF6 deficiency enhances organ damage, as proven by the more severe functional damage and poorer prognosis exhibited in ATF6 knockout mice following cerebral ischemia." (PMID 39329905, 2024). "It was also found that in a cerebral ischemia animal and reoxygenation cell models, taurine can inhibit the activation of ATF6, inhibit ERS, reduce cell apoptosis, and exert a neuroprotective effect after cerebral ischemia/reperfusion." (PMID 35602556, 2022). "Unfortunately, there are fewer studies on the ATF6 branch in the ER stress after cerebral ischemia than the PERK and IRE1 arm given its difficult to detect." (PMID 34408630, 2021). "In this context, very recently, an activator of ATF6 was tested and it was found as protective in several pathologies such as renal/cerebral ischemia and proteins aggregation-related diseases." (PMID 31671908, 2019). "Pharmacological activation of ATF6 is also protective in renal and cerebral ischemia/reperfusion models, demonstrating its widespread utility." (PMID 30643122, 2019). "In summary, our findings demonstrated that AA147-induced activation of the ATF6 and Nrf2 pathways ameliorated post-cardiac arrest cerebral ischemia/reperfusion injury, improving neurological outcomes and reducing neuronal death by suppressing ER stress-associated apoptosis and oxidative stress." (PMID 36506549, 2022). "Treatment strategy based on protein homeostasis induced by ATF6 may restore the injury of insecure proteostasis cerebral ischemia." (PMID 34408630, 2021). "Recently, ATF6 was proposed to play a central role in renal and cerebral ischemia." (PMID 31671908, 2019). "In addition, the activation of ATF6 branch of the UPR was also reported to improve the outcomes after cerebral ischemia." (PMID 30283292, 2018). "Furthermore, the cytoprotective properties of ATF6 have been demonstrated in the context of human disorders ranging from cardiac and brain ischemia, to glomerular disease." (PMID 29801500, 2018). "In some ways, the permanent brain ischemia significantly enhanced the ER stress through PERK/eIF2α/ATF4, ATF6 and IRE-1/NF-κB/JNK/p38 signaling." (PMID 29970982, 2018). "Not only in cerebral ischemia models, but also myocardial ischemia, renal ischemia, and other ischemic models, the protective effect appears in the cell homeostasis of the pharmacological ATF6 reprogramming protein induced by a compound called 147 and disappears after the absence of specific ATF6." (PMID 34408630, 2021). "During cerebral ischemia, the lack of the canonical UPR may destine the cell to death because of the lack of transcriptional and translational response afforded when IRE and ATF6 are activated." (PMID 25830481, 2015).
neuroblastoma (12 papers, 2014 to 2025). Neuroblastoma (NB) is the most common solid, extracranial childhood tumor. "The results obtained on neuroblastoma cells, by Western blotting analysis, showed that total ATF6 expression increased in cells pretreated at 1 h and 4 h with TG compared with control cells, confirming the induction of reticular stress and the onset of UPR." (PMID 39329905, 2024). "Another study showed that rotenone increased the cleavage of ATF6 and phosphorylation of eIF2α, leading to an increase in apoptosis in neuroblastoma cells." (PMID 37529115, 2023). "Therefore, we further investigated the relationship between ERVW-1 and ATF6 using the human neuroblastoma cell line SH-SY5Y." (PMID 37376599, 2023). "In this study, we found that SB202190 selectively activates PERK independently of its inhibition of p38 mitogen-activated protein kinase, but not inositol-requiring transmembrane kinase/endoribonuclease-1α (IRE1α) or activating transcription factor 6 (ATF6), in human neuroblastoma cells." (PMID 35166693, 2022). "Previous in vitro studies have shown increased processing and nuclear translocation of ATF6 in N2a neuroblastoma cells overexpressing mutant SOD1G85R and an increase in SOD1 aggregates in the motoneuronal cell line NSC-34 following ATF6 knockdown." (PMID 37958767, 2023). "Therefore, we investigated the relationship among ERVW-1, ATF6, and XBP1 with cytological experiments using the neuroblastoma cell line SH-SY5Y." (PMID 37376599, 2023). "ER stress (tunicamycin) activated three branches of the UPR; the PERK, IRE1α, and ATF6 branches, as indicated by the induction of CHOP transcription, XBP1 splicing, and HERP expression, respectively, in the SH-SY5Y neuroblastoma cell line." (PMID 24421337, 2014). "In addition, our data show that SB202190-induced ALP activation is dependent on PERK but not IRE1α and ATF6 in human neuroblastoma cells." (PMID 35166693, 2022). "The small molecule BIX induces BiP expression through an ATF6-dependent mechanism, but does not substantially induce expression of other ATF6 target genes, such as Grp94 and PDIA4 in SK-N-SH neuroblastoma cells." (PMID 30481215, 2018).
bladder cancer (11 papers, 2021 to 2025). "The detachment of the chaperone HSPA5 from the luminal portion of the ER integral membrane proteins EIF2AK3, ERN1, and ATF6 is a crucial process in the activation of ER stress in human leukemia and bladder carcinoma cell lines." (PMID 39000233, 2024). "In turn, accumulation of Golgi TPD52 in bladder cancer cells appears to directly result in the cleavage of ATF6." (PMID 39401430, 2024). "OTUB1 interacts with ATF6 and enhances its stability by inhibiting ubiquitination, thereby promoting the migration and proliferation of bladder cancer cells." (PMID 35959432, 2022). "Similarly, flaccidoxide-13-acetate, isolated from cultured soft coral Sinularia gibberosa, was found to provoke ERS and activate the PERK–eIF2α–ATF6–CHOP pathway, causing inhibitory effects against the invasion and migration of bladder cancer cells." (PMID 34136492, 2021). "Additionally, some studies reported that OTUB1 promotes the progression of bladder cancer through its interaction with ATF6, and that ATF6 could facilitate cervical cancer cell growth and migration through the MAPK pathway, resulting in poor cancer prognosis." (PMID 35222510, 2021). "In research on bladder cancer, it was found that OTUB1 stabilizes 90 kDa ATF6 (p90) by inhibiting its ubiquitination, consequently activating the ATF6 signal pathway." (PMID 40869379, 2025). "To determine whether GANAB was involved in the regulation of ERS signaling, we conducted experiments to quantitate the transcriptional activation of ATF6 by using siRNA-mediated GANAB knockdown in bladder cancer cell lines with/without tunicamycin (Tm) stimulation." (PMID 35879690, 2022).
cervical cancer (11 papers, 2013 to 2025). A primary or metastatic malignant neoplasm involving the cervix. "In cervical cancer models, ATF6 has been shown to induce EMT by suppressing E-cadherin expression while increasing the levels of mesenchymal markers such as Snail155." (PMID 41209558, 2025). "Further, the inhibitory effect of ATF6 knockdown on the proliferation of two cervical cancer cell lines was demonstrated." (PMID 38482016, 2024). "The upregulation of ATF6 in cervical cancer cells promotes their proliferation and inhibit apoptosis." (PMID 37790807, 2023). "Moreover, investigations conducted on cervical cancer cells have discovered that ATF6 facilitates cellular migration, EMT, and in vitro cell viability." (PMID 40035165, 2025). "Moreover, ATF6 has been demonstrated to accelerate the proliferation of cervical cancer cells via the MAPK pathway." (PMID 39080273, 2024). "However, further extensive research is required to improve our understanding of the function of ATF6 in cervical cancer in vivo and the clinical context." (PMID 39188936, 2024). "The results of the Transwell experiment showed that the number of cells penetrating the lower chamber was significantly reduced after ATF6 gene knockdown, indicating that ATF6 gene knockdown significantly inhibited the migration and invasion ability of cervical cancer cells." (PMID 38482016, 2024). "For instance, in a cervical cancer model, the ATF6 branch of UPR can promote EMT and further tumor invasion and metastasis by reducing the expression of E-cadherin and upregulating the expression of the major transcription proteins Snail and vimentin through the MARK signaling pathway." (PMID 39080273, 2024). "In vitro studies suggest that ATF6 may promote cell growth, migration, and autophagy in cervical cancer through ER stress and MAPK signaling pathways." (PMID 39188936, 2024). "Similarly, in tumors of the female reproductive system, ATF6 is highly expressed in cervical cancer cells." (PMID 37790807, 2023). "Moreover, ATF6 promotes cervical cancer cell proliferation via the MAPK pathway." (PMID 41209558, 2025). "ATF6 inhibits autophagy but promotes EMT through the MAPK signaling pathway, which is a possible reason for the chemoresistance of cervical cancer cells." (PMID 37790807, 2023). "Park and Ozcan pointed out that ERS regulated the survival or apoptosis of tumor cells through IRE1α–XBP1, PERK–eIF2α, and ATF6 pathways, and ERS was activated in the occurrence and development of cervical cancer." (PMID 36406049, 2022). "However, studies on ATF6 found that ATF6 promotes the proliferation and migration through ER stress and MAPK pathways in cervical cancer cells in vitro." (PMID 40035165, 2025). "ATF6 activation drives TRIM37 transcription, enhancing malignancy in cervical cancer cells." (PMID 40158112, 2025).
myocardial ischemia (11 papers, 2018 to 2025). A disorder of cardiac function caused by insufficient blood flow to the muscle tissue of the heart. "ATF6α also contributes to myocardial adaptation to chronic hypoxia and reduces myocardial ischemia/reperfusion injury." (PMID 40223122, 2025). "ATF6, another crucial transcriptional regulator of ER proteostasis, was also reported to facilitate myocardial ischemia/reperfusion injury." (PMID 37693833, 2023). "ATF6 decreases myocardial ischemia/reperfusion damage and links ER stress and oxidative stress signaling in the cardia myocytes." (PMID 38007457, 2023). "On the other hand, Jin and colleagues previously reported ATF6 as a link between ER stress and oxidative stress in myocardial ischemia." (PMID 35162959, 2022). "One potential beneficial effect of ATF6 activation is supported by a recent study showing that ATF6 decreases myocardial ischemia/reperfusion damage." (PMID 30515102, 2018). "Available data shows ATF6 was involved in unfolded protein responses related to reticulum stress via the direct induction of antioxidant proteins, and plays an important role in protecting myocardial ischemia injury." (PMID 30618737, 2018). "These previous findings suggested that ATF6 is required for adaptive ER stress response gene induction and activation of the ATF6 branch of UPR has protective effects during myocardial ischemia." (PMID 30232231, 2018).
pancreatic cancer (11 papers, 2014 to 2025). "As such, pancreatic tumor tissues have higher Bip and ATF-6 expression levels than the normal pancreatic tissues." (PMID 36276125, 2022). "In pancreatic cancer, however, ATF6 may plays a pro-apoptotic role." (PMID 34659567, 2021). "The expression of ER stress markers such as GRP78, ATF6, IRE1 and PERK was evaluated in all the pancreatic cancer cells." (PMID 34586588, 2021). "The up-regulation of ATF6 was related to the worse recurrence-free survival (RFS), overall survival (OS), and disease-specific survival (DSS) of pancreatic cancer patients; in addition, ATF6 promoted the proliferation and invasion of pancreatic cancer cells." (PMID 38896161, 2024). "Fisetin in murine xenograft pancreatic cancer PANC‐1 cells inhibits PANC‐1 cell proliferation, enhances AMPK/mTOR signaling pathway and stress‐induced transcription factor p8, induces autophagy, and increases the ATF4 and ATF6." (PMID 33473265, 2021). "In addition, we demonstrated that pancreatic cancer cells expressed high levels of genes belonging to the ER stress/UPR system including proximal signal sensors (PERK, ATF6 and ERN1), the chaperone lectins (Calnexin) and the folding catalysts (PDI)." (PMID 25657029, 2015).
asthma (10 papers, 2013 to 2025). "In the lung, ORMDL3 activates the UPR via the ATF6 pathway, increasing transcription of endoplasmic reticulum–associated protein degradation pathway-specific genes (Edem-1) and regulating the expression of IL-6, which has been implicated in the pathogenesis of asthma." (PMID 27623174, 2017). "Increased ATF6 expression has been shown in animal models of asthma and bleomycin-induced pulmonary fibrosis, but its role in VILI and ARDS has not been studied." (PMID 30134920, 2018). "Specifically, IL-6 is elevated in individuals with asthma and is also regulated by ATF6 during activation of the UPR." (PMID 23369242, 2013). "the ATF6 inhibitor Ceapin-A7 remains preclinical/early-phase with supportive murine data showing reduced eosinophilia/neutrophilia and potential relevance to steroid-resistant/T2-low asthma." (PMID 41459491, 2025). "In mice, ORMDL3 expression has been shown to be induced by allergen, IL-4 and IL-13 via STAT6 and in bronchial epithelial cells, overexpression of ORMDL3 has been shown to trigger activating transcription factor 6 (ATF6), which has also been implicated in airway remodeling in asthma." (PMID 35386986, 2021). "An increase in ER stress markers including ATF4, ATF6, CHOP, GRP78, and XBP1 has been detected in those with ovalbumin-induced asthma." (PMID 39295946, 2024). "Additionally, we demonstrated that ORMDL3 selectively regulates the ATF6 UPR-autophagy signaling pathway, which is an important mechanism to link ORMDL3 to mast cell physiology providing a cellular and molecular explanation for the association between ORMDL3 and asthma pathogenesis." (PMID 33679742, 2021). "It is unclear if UPR signaling is abnormally regulated in asthma, although ORMDL3 has been shown to be increased in asthmatic bronchial epithelial cells, which leads to increased ATF6-mediated ER stress and UPR." (PMID 29472925, 2018). "They reported that in vitro overexpression of ORMDL3 activated the ATF6 pathway of the UPR and induced expression of several genes with potential importance in the pathogenesis of asthma." (PMID 23369242, 2013). "The ATF6 inhibitor Ceapin A7 suppressed downstream UPR genes and Th cytokines in human and murine memory CD4+ T cells, and in chronic asthma models reduced eosinophilia and neutrophilia, indicating potential for steroid-resistant and T2-low asthma." (PMID 41459491, 2025).